INO80C (INO80 complex subunit C)
Description:
Proposed core component of the chromatin remodeling INO80 complex which is involved in transcriptional regulation, DNA replication and probably DNA repair.
Synonyms: hIes6; C18orf37; FLJ38183; IES6
Tractability: Small molecule: a structure with a bound ligand is known. PROTAC: ubiquitination databases record sites on it.
Gene: Protein-coding gene on chromosome 18 (35,452,230 to 35,497,979, reverse strand). Ensembl gene ENSG00000153391.
Subcellular location: Nucleus
Subcellular location (Human Protein Atlas): Nucleoplasm; Cytosol; Nucleoli fibrillar center; Vesicles
Pathways (Reactome):
DNA Repair: DNA Damage Recognition in GG-NER
Metabolism of proteins: UCH proteinases
Gene Ontology:
Molecular function: protein binding
Biological process: chromatin remodeling; positive regulation of DNA-templated transcription; regulation of cell cycle; regulation of chromosome organization; regulation of DNA replication; regulation of DNA strand elongation; positive regulation of DNA repair; positive regulation of telomere maintenance in response to DNA damage; regulation of DNA repair; regulation of embryonic development; telomere maintenance
Cellular component: fibrillar center; Ino80 complex; MLL1 complex; nucleoplasm; nucleus
Genetic constraint (gnomAD): Loss-of-function variants: 8 observed, 8.36 expected, observed/expected ratio (o/e) 0.96, 90% interval 0.56 to 1.67. That is too few expected variants to judge how well the gene tolerates losing a copy. Missense variants: 186 observed, 187.28 expected, observed/expected ratio (o/e) 0.99, 90% interval 0.88 to 1.12. Synonymous variants: 84 observed, 78.92 expected, observed/expected ratio (o/e) 1.06, 90% interval 0.89 to 1.28.
Homologues: Orthologues: chimpanzee INO80C (100% identical), macaque INO80C (98% identical), dog INO80C (95% identical), pig INO80C (95% identical), guinea pig INO80C (93% identical), rat Ino80c (91% identical), mouse Ino80c (91% identical), zebrafish ino80c (61% identical), Drosophila melanogaster CG12659 (27% identical).
Diseases named in the same sentence as INO80C in open-access papers:
INO80C is named in the same sentence as 4 diseases in open-access papers, as found by Europe PMC text mining. Sharing a sentence is not in itself a finding about the gene and the disease. The quoted sentences say what the papers report.
bone metastasis (1 paper, 2021). Transfer of a neoplasm from its primary site to bones. "SMOX-58,619-AP (p = 0.015), INO80C-45,170-AP (p = 0.022) and ITGB4-43,489-ES (p = 0.048) were found to be significantly related to both bone metastasis and OS in the Venn plot." (PMID 34402716, 2021).
liver cancer (1 paper, 2018). An epithelial or non-epithelial malignant neoplasm that arises from the liver. "To investigate the factors that influence INO80-C function throughout the genome, we performed ChIP-seq for 4 subunits of INO80-C in the liver cancer cell line HepG2." (PMID 29432129, 2018).
INO80C also shares sentences with these, for which no sentence is quoted: Azoospermia (1 paper); tumor (1).